SLC5A3 (solute carrier family 5 member 3)
Description:
Electrogenic Na(+)-coupled sugar symporter that actively transports myo-inositol and its stereoisomer scyllo-inositol across the plasma membrane, with a Na(+) to sugar coupling ratio of 2:1 (By similarity). Maintains myo-inositol concentration gradient that defines cell volume and fluid balance during osmotic stress, in particular in the fetoplacental unit and central nervous system (By similarity). Forms coregulatory complexes with voltage-gated K(+) ion channels, allosterically altering ion selectivity, voltage dependence and gating kinetics of the channel. In turn, K(+) efflux through the channel forms a local electrical gradient that modulates electrogenic Na(+)-coupled myo-inositol influx through the transporter. Associates with KCNQ1-KCNE2 channel in the apical membrane of choroid plexus epithelium and regulates the myo-inositol gradient between blood and cerebrospinal fluid with an impact on neuron excitability (By similarity). Associates with KCNQ2-KCNQ3 channel altering ion selectivity, increasing Na(+) and Cs(+) permeation relative to K(+) permeation. Provides myo-inositol precursor for biosynthesis of phosphoinositides such as PI(4,5)P2, thus indirectly affecting the activity of phosphoinositide-dependent ion channels and Ca(2+) signaling upon osmotic stress.
Synonyms: SMIT1; SMIT; BCW2; SMIT2
Tractability: Small molecule: it belongs to a druggable protein family. Antibody: its Gene Ontology location is reachable by antibodies, with high confidence; UniProt places it where antibodies can reach, with medium confidence; UniProt predicts a signal peptide or a membrane-spanning region; the Human Protein Atlas places it where antibodies can reach. PROTAC: ubiquitination databases record sites on it; its protein half-life has been measured.
Gene: Protein-coding gene on chromosome 21 (34,073,578 to 34,106,260, forward strand). Ensembl gene ENSG00000198743.
Subcellular location: Apical cell membrane; Basolateral cell membrane
Subcellular location (Human Protein Atlas): Plasma membrane
Pathways (Reactome):
Transport of small molecules: Inositol transporters
Gene Ontology:
Molecular function: myo-inositol:sodium symporter activity; potassium channel regulator activity; protein binding; transmembrane transporter binding; D-glucose:sodium symporter activity; fucose transmembrane transporter activity; myo-inositol transmembrane transporter activity; pentose transmembrane transporter activity; polyol transmembrane transporter activity; solute:sodium symporter activity; transmembrane transporter activity
Biological process: D-glucose transmembrane transport; fucose transmembrane transport; myo-inositol import across plasma membrane; myo-inositol transport; pentose transmembrane transport; polyol transmembrane transport; positive regulation of protein localization to membrane; positive regulation of reactive oxygen species biosynthetic process; transport across blood-brain barrier; sodium ion transmembrane transport; transmembrane transport
Cellular component: perinuclear region of cytoplasm; plasma membrane; apical plasma membrane; basolateral plasma membrane; membrane
Genetic constraint (gnomAD): Loss-of-function variants: 10 observed, 45.53 expected, observed/expected ratio (o/e) 0.22, 90% interval 0.13 to 0.37. The upper end of that interval is the gene's LOEUF score, 0.37, which puts it in group 1 of 6, group 1 being the genes least tolerant of losing a copy. Missense variants: 608 observed, 943.37 expected, observed/expected ratio (o/e) 0.64, 90% interval 0.6 to 0.69. Synonymous variants: 349 observed, 339.58 expected, observed/expected ratio (o/e) 1.03, 90% interval 0.94 to 1.12.
Homologues: Orthologues: guinea pig SLC5A3 (95% identical), mouse Slc5a3 (94% identical), rat Slc5a3 (93% identical), zebrafish slc5a3b (65% identical), zebrafish slc5a3a (62% identical), Drosophila melanogaster CG33124 (14% identical), Drosophila melanogaster CG31668 (14% identical), Drosophila melanogaster bumpel (14% identical), Drosophila melanogaster CG31262 (14% identical), Drosophila melanogaster kumpel (14% identical), Drosophila melanogaster CG2187 (13% identical), Drosophila melanogaster SLC5A11 (13% identical), and 3 more. Paralogues in human: SLC5A9 (45% identical), SLC5A11 (44% identical), SLC5A1 (44% identical), SLC5A2 (42% identical), SLC5A4 (40% identical), SLC5A10 (39% identical), SLC5A12 (18% identical), SLC5A8 (18% identical), SLC5A6 (17% identical), SLC5A5 (16% identical), SLC5A7 (13% identical).
Diseases named in the same sentence as SLC5A3 in open-access papers:
SLC5A3 is named in the same sentence as 56 diseases in open-access papers, as found by Europe PMC text mining. Sharing a sentence is not in itself a finding about the gene and the disease. The quoted sentences say what the papers report.
diabetes (4 papers, 2019 to 2023). "An increasing number of studies indicate that SLC5A3 plays an important role in diabetes-related metabolism." (PMID 35299963, 2022). "Additional studies are required to clarify the role of SLC5A3 in IGT and diabetes." (PMID 37758822, 2023).
atherosclerosis (3 papers, 2017 to 2024). A disease characterized by the build-up of fatty material and calcium deposition in the arterial wall resulting in partial or complete occlusion of the arterial lumen. "By MR analysis, these DEGs (e.g., MRAS, MRPS6, and SLC5A3) were linked to causal effects with adverse outcomes in atherosclerosis and MI." (PMID 39766313, 2024). "Notably, MRAS, MRPS6, and SLC5A3 were specifically associated with both atherosclerosis and MI risk." (PMID 39766313, 2024). "MR analysis identified the causal relationship between foamy cell fate A-related genes (MRAS, MRPS6, and SLC5A3) and the incidence of atherosclerosis and myocardial infarction." (PMID 39766313, 2024). "Of these genes, A2ML1, AGGF1, CBS, ECE1, GABRB3, GALNT2, MRPS6/SLC5A3, and SPG7 had documented associations with hypertension, ischemic stroke and methionine metabolism, atherosclerosis, and early-onset MI." (PMID 34252155, 2021). "However, as there may be a number of pathways which contribute to atherosclerosis yet to be elucidated (indicated by the number of GWAS hits with unknown mechanisms), the involvement of SLC5A3 cannot be discounted." (PMID 28458444, 2017).
inclusion body myositis (3 papers, 2020 to 2023). A slowly progressive degenerative inflammatory disorder of skeletal muscles characterized by late onset weakness of specific muscles and distinctive histopathological features. "Besides, SLC5A3 (solute carrier family 5 member 3) was proved to be promote inflammatory responses in inclusion body myositis (IBM)." (PMID 33043022, 2020).
acute myeloid leukemia (2 papers, 2022 to 2023). Acute myeloid leukemia (AML) is a group of neoplasms arising from precursor cells committed to the myeloid cell-line differentiation. "For example, SLC5A3-dependent MI transport, which promotes nutrient dependency, is required for acute myeloid leukemia (AML) cell proliferation." (PMID 37324953, 2023).
anemia (2 papers, 2011 to 2023). A reduction in the number of red blood cells, the amount of hemoglobin, and/or the volume of packed red blood cells. "Regarding SMIT1, a mutation in SLC5A3 has been identified as a progressive anemia in ponies called fatal Foal Immunodeficiency Syndrome." (PMID 37047055, 2023).
cervical cancer (2 papers, 2018 to 2023). A primary or metastatic malignant neoplasm involving the cervix. "Analysis of TCGA cervical cancer datasets revealed that patients with cervical cancer exhibiting SLC5A3 upregulation were associated with poor overall survival (P = 0.065) and progression-free interval (PFI) (P = 0.001)." (PMID 37324953, 2023). "This study examined the role of SLC5A3, a myo-inositol transporter, in the pathogenesis of cervical cancer." (PMID 37324953, 2023). "The SLC5A3 mRNA and protein expression levels were downregulated upon TonEBP knockdown but were upregulated upon ectopic TonEBP overexpression in cervical cancer cells." (PMID 37324953, 2023). "The LinkedOmics functional model was used to examine genes co-expressed with SLC5A3 in TCGA cervical cancer cohort." (PMID 37324953, 2023). "TonEBP (NFAT5) was the second top differentially expressed gene (DEG) that was positively correlated with SLC5A3 expression in TCGA cervical cancer cohort." (PMID 37324953, 2023). "This study demonstrated that cellular MI contents were upregulated in SLC5A3 knockdown/KO cervical cancer cells but were upregulated in SLC5A3-overexpressing cells." (PMID 37324953, 2023). "SLC5A3 knockdown or KO suppressed cervical cancer cell viability, proliferation, and migration and induced cell death and apoptosis." (PMID 37324953, 2023). "In vivo studies showed that intratumoral injection of SLC5A3 shRNA-expressing virus arrested cervical cancer xenograft growth in mice." (PMID 37324953, 2023). "Together, overexpressed SLC5A3 promotes growth of cervical cancer cells, representing as a novel therapeutic oncotarget for the devastating disease." (PMID 37324953, 2023). "The Akt-mTOR cascade was inhibited in sh-SLC5A3 AAV-injected cervical cancer xenograft tissues and SLC5A3 KO xenograft tissues." (PMID 37324953, 2023). "MI was also downregulated in sh-SLC5A3 AAV-injected or koSLC5A3 (sg1)-injected cervical cancer xenograft tissues." (PMID 37324953, 2023). "The ROS and oxidative stress levels were upregulated in SLC5A3 knockdown cervical cancer cells and SLC5A3 knockdown/KO xenograft tissues." (PMID 37324953, 2023). "Transduction of sh-TonEBP AAV construct downregulated SLC5A3 expression and inhibited pCCa-1 cervical cancer xenograft growth." (PMID 37324953, 2023). "The receiver operating characteristic curve analysis suggested that SLC5A3 upregulation can predict the 1-5 year survival rates of cervical cancer patients." (PMID 37324953, 2023). "SLC5A3 knockdown/KO significantly decreased the phosphorylation of Akt1 and S6K in primary cervical cancer cells." (PMID 37324953, 2023). "The results of ChIP assay revealed that the binding of TonEBP to the proposed SLC5A3 promoter 35 was significantly upregulated in the cervical cancer tissues of four patients but was relatively low in matched adjacent non-cancerous cervical epithelial tissues." (PMID 37324953, 2023). "Through boinformatics analysis, we showed that the SLC5A3 mRNA levels were upregulated in cervical cancer tissues." (PMID 37324953, 2023). "Lentiviral SLC5A3 overexpression construct transduction upregulated the cellular myo-inositol level and promoted Akt-mTOR activation, enhancing cervical cancer cell proliferation and migration." (PMID 37324953, 2023). "In contrast, supplementation of myo-inositol or n-acetyl-L-cysteine or transduction of a constitutively active Akt1 construct mitigated SLC5A3 KO-induced cytotoxicity in cervical cancer cells." (PMID 37324953, 2023). "The CellROX dye intensity was upregulated in pCCa-1 cervical cancer cells transduced with sh-SLC5A3 (seq1) or koSLC5A3 (sg1)." (PMID 37324953, 2023). "In primary/established cervical cancer cells, SLC5A3 shRNA/knockout (KO) exerted growth-inhibitory effects and promoted cell death/apoptosis." (PMID 37324953, 2023). "The reactivation of Akt-mTOR by caAkt1 suppressed SLC5A3 KO-induced cervical cancer cell death." (PMID 37324953, 2023).
cervical cancer (continued). "This study demonstrated that TonEBP is the key transcription factor for SLC5A3 in cervical cancer." (PMID 37324953, 2023). "Bioinformatics analysis revealed that SLC5A3 is upregulated in cervical cancer tissues." (PMID 37324953, 2023). "MI supplementation alleviated SLC5A3 KO-induced apoptosis and cell death in cervical cancer cells." (PMID 37324953, 2023). "Thus, SLC5A3 mediates cervical cancer cell growth, at least partially, by promoting Akt-mTOR activation." (PMID 37324953, 2023). "Furthermore, SLC5A3 knockdown or KO downregulated myo-inositol levels, induced oxidative injury, and decreased Akt-mTOR activation in cervical cancer cells." (PMID 37324953, 2023). "Therefore TonEBP-SLC5A3 promoter DNA binding increasing in cervical cancer is key for SLC5A3 upregulation." (PMID 37324953, 2023). "The anti-oxidant NAC suppressed SLC5A3 KO-induced cytotoxicity against cervical cancer cells." (PMID 37324953, 2023). "The binding of TonEBP to the SLC5A3 promoter was upregulated in cervical cancer." (PMID 37324953, 2023). "SLC5A3 upregulation was confirmed in clinical cancer tissues and different cervical cancer cells." (PMID 37324953, 2023). "SLC5A3 KO also inhibited pCCa-1 cervical cancer xenograft growth." (PMID 37324953, 2023). "In this study, SLC5A3 knockdown or KO upregulated oxidative stress in cervical cancer cells." (PMID 37324953, 2023). "The binding of TonEBP to the SLC5A3 promoter was upregulated in various cervical cancer tissues/cells and may contribute to SLC5A3 upregulation." (PMID 37324953, 2023). "SLC5A3 mRNA and protein expression was significantly upregulated in the primary human cervical cancer cells (pCCa-1/-2/-3 cells, which were obtained from Dr. Cao 18) and the immortalized HeLa cells, but were low in the cervical epithelial cells (HCerEpC1 18 and Ect1/E6E7 cells)." (PMID 37324953, 2023). "This study demonstrated that SLC5A3 overexpression promoted cervical cancer cell growth." (PMID 37324953, 2023). "The upregulated SLC5A3 promotes cervical cancer cell growth." (PMID 37324953, 2023). "The upregulated SLC5A3 mRNA and protein levels in cervical cancer contribute to cancer cell growth." (PMID 37324953, 2023). "We further hypothesized that silencing of the transcription factor TonEBP should downregulate SLC5A3 expression and inhibit cervical cancer cell in vivo growth." (PMID 37324953, 2023). "We hypothesized that SLC5A3 is an important oncogenic gene for cervical cancer." (PMID 37324953, 2023). "Thus, SLC5A3 depletion exerts anti-cervical cancer effects by inducing oxidative stress." (PMID 37324953, 2023). "Thus, bioinformatics analysis revealed that SLC5A3 is upregulated in cervical cancer." (PMID 37324953, 2023). "Thus, SLC5A3-dependent MI import is critical for cervical cancer cell growth." (PMID 37324953, 2023). "Thus, the effect of SLC5A3 knockdown on cervical cancer cell apoptosis was examined." (PMID 37324953, 2023). "Thus, TonEBP upregulates SLC5A3 expression and promotes cervical cancer cell growth." (PMID 37324953, 2023). "Thus, SLC5A3 KO significantly impaired pCCa-1 cervical cancer xenograft growth." (PMID 37324953, 2023). "Similarly, SLC5A3 KO also inhibited pCCa-1 cervical cancer xenograft growth." (PMID 37324953, 2023).
HbH disease (2 papers, 2024 to 2025). "This study also found that METTL16 and SLC5A3 mRNA were down-regulated in HbH-CS disease patients compared with other types of HbH disease patients (—SEA/ αWS α,—SEA/- α3.7,—SEA/- α4.2)." (PMID 39088431, 2024). "The downregulation of METTL16 and SLC5A3 mRNA in HbH disease patients may be a compensatory response, which can reduce the elevated ROS caused by iron deposition and oxidative stress." (PMID 39088431, 2024). "YTHDF3 may read the m6A modification information of SLC5A3 mRNA, affect its protein expression regulate ROS synthesis and intracellular iron content in red blood cells and thus participate in the pathological and physiological processes of HbH disease." (PMID 39088431, 2024). "We verified the methylation level of the SLC5A3 target site in eight patients with HbH disease and four normal controls." (PMID 39088431, 2024). "We can also develop drugs for the METTL16_ YTHDF3_ SLC5A3 pathway, such as agents designed to regulate METTL16 to reduce ROS and change the expression of IGF2BP3 to improve haemoglobin, which will provide a new direction for the treatment of HbH disease." (PMID 39088431, 2024).
lung carcinoma (2 papers, 2016 to 2020). "The results suggested that PEPD, SLC15A1, and SLC5A3 were candidates for individual lethal genes specific to lung cancer, and pairs of CBS-SLC7A11, CBS-SLC3A2, CMPK1-PTDSS1, CMPK1-PLD2 were candidate synergistic lethal genes specific in the tumors." (PMID 32085724, 2020).
muscular dystrophies (2 papers, 2020 to 2022). "Overexpressed SLC5A3 has also been observed in other inflammatory myopathies and in muscular dystrophies." (PMID 32235474, 2020).
brain tumors (1 paper, 2022). "Biopsy analysis of GBM also revealed expression of the proteins SLC5A1 and SLC5A3 in brain tumors." (PMID 36497276, 2022).
colorectal cancer (1 paper, 2022). A primary or metastatic malignant neoplasm that affects the colon or rectum. "Using DepMap data, we observed that the most extreme effect of SLC5A3 down-regulation was found in ALL cell lines (one-tailed Wilcoxon test p-value = 0.0363); however, we could not demonstrate a similar performance in colorectal cancer." (PMID 35286311, 2022).
congenital heart defects (1 paper, 2025). "Deletions in SYNJ1, ITSN1, SLC5A3/SMIT1, and KCNE2, located in the distal part of 21q22.11, are associated with neurobehavioral symptoms, whereas deletions in the critical region 21q22.11, such as KCNE1 and DSCR1, lead to congenital heart defects." (PMID 41510431, 2025).
hepatocellular carcinoma (1 paper, 2021). A malignant tumor that arises from hepatocytes. "Upon initial exploration of the relationship between this gene and hepatocellular carcinoma cell (HCC), we observed that YAP, OGT, SLC5A3, and Nudt9 expression in HCC tissues was upregulated relative to that in normal liver tissues through The Cancer Gene Atlas (TCGA) online visualization website." (PMID 34588426, 2021).
leukemia (1 paper, 2024). A malignant (clonal) hematologic disorder, involving hematopoietic stem cells and characterized by the presence of primitive or atypical myeloid or lymphoid cells in the bone marrow and the blood. "SLC5A3 protein is crucial for leukemia cells with high nutritional requirements and a relative lack of inositol." (PMID 39088431, 2024).
liver cancer (1 paper, 2021). An epithelial or non-epithelial malignant neoplasm that arises from the liver. "Activation of the HBP pathway is the foundation of enhancing the O-GlcNAcylation level in liver cancer cells, and Nudt9 and SLC5A3 are key genes of the HBP pathway." (PMID 34588426, 2021). "We found that the expression of SLC5A3 and Nudt9 was positively associated with YAP and that their levels were elevated in liver cancer tissues." (PMID 34588426, 2021). "Also, we found higher levels of YAP OGT, SLC5A3, Nudt9, and O-GlcNAcylation in liver cancer tissues than in peritumoral tissues." (PMID 34588426, 2021). "Our previous research stated that, in an HG environment, after the level of YAP in liver cancer cells increased, global cellular O-GlcNAcylation could be upregulated through the regulation of Nudt9, SLC5A3, and OGT." (PMID 34588426, 2021). "However, CA reduced the expression of Nudt9, SLC5A3, OGT, YAP, and O-GlcNAcylation in liver cancer cells cultured in HG." (PMID 34588426, 2021).
malignant melanoma (1 paper, 2025). "We were excited to find for the first time that FCGR2, CHRDL1, SLC5A3 are associated with the prognosis of melanoma." (PMID 40652057, 2025). "We verified the expression of SLC5A3, which had no reported association with tumors, was higher in melanoma tissues than normal tissues using WB and immunohistochemical (IHC) experiment." (PMID 40652057, 2025). "Furthermore, we also find if SLC5A3 is knocked out, the proliferation capacity of melanoma cells will decrease." (PMID 40652057, 2025). "Interestingly, SLC5A3 was mainly expressed in malignant melanoma cells." (PMID 40652057, 2025). "The qRT-PCR results showed that the expression levels of four genes, FCGR2, GBP4, SLC5A3 and GJA1, in melanoma cells were different from that in normal melanocyte, which was consistent with the statistical results of the samples we obtained in the public database." (PMID 40652057, 2025).
myositis (1 paper, 2020). "Its Na+/myo-inositol co-transporter SLC5A3 is expressed in muscle tissue and further accumulates in myositis." (PMID 32235474, 2020).